PDXK (pyridoxal kinase)
Description:
Catalyzes the phosphorylation of the dietary vitamin B6 vitamers pyridoxal (PL), pyridoxine (PN) and pyridoxamine (PM) to form pyridoxal 5'-phosphate (PLP), pyridoxine 5'-phosphate (PNP) and pyridoxamine 5'-phosphate (PMP), respectively (Probable). PLP is the active form of vitamin B6, and acts as a cofactor for over 140 different enzymatic reactions.
Synonyms: C21orf124; C21orf97; PKH; PNK; PRED79; FLJ21324; FLJ31940; MGC15873; HEL-S-1a; HMSN6C
Tractability: Small molecule: a structure with a bound ligand is known; a high-quality ligand is known; it has a high-quality binding pocket. Antibody: its Gene Ontology location is reachable by antibodies, with high confidence. PROTAC: ubiquitination databases record sites on it; its protein half-life has been measured; a small molecule that binds it is known.
Target class: Enzyme; Transferase
Gene: Protein-coding gene on chromosome 21 (43,719,094 to 43,762,307, forward strand). Ensembl gene ENSG00000160209.
Subcellular location: Cytoplasm, cytosol
Subcellular location (Human Protein Atlas): Nucleoplasm
Pathways (Reactome):
Immune System: Neutrophil degranulation
Metabolism: Vitamin B6 activation to pyridoxal phosphate
Gene Ontology:
Molecular function: ATP binding; lithium ion binding; magnesium ion binding; potassium ion binding; protein homodimerization activity; pyridoxal kinase activity; pyridoxal phosphate binding; sodium ion binding; zinc ion binding; phosphotransferase activity, alcohol group as acceptor
Biological process: pyridoxal 5'-phosphate salvage; vitamin B6 metabolic process
Cellular component: cytosol; extracellular exosome; nucleoplasm; nucleus; extracellular region; secretory granule lumen; specific granule lumen
Genetic constraint (gnomAD): Loss-of-function variants: 10 observed, 28.41 expected, observed/expected ratio (o/e) 0.35, 90% interval 0.22 to 0.6. The upper end of that interval is the gene's LOEUF score, 0.6, which puts it in group 2 of 6, group 1 being the genes least tolerant of losing a copy. Missense variants: 285 observed, 325.32 expected, observed/expected ratio (o/e) 0.88, 90% interval 0.79 to 0.97. Synonymous variants: 137 observed, 130.43 expected, observed/expected ratio (o/e) 1.05, 90% interval 0.91 to 1.21.
Homologues: Orthologues: macaque PDXK (97% identical), chimpanzee PDXK (96% identical), dog PDXK (88% identical), guinea pig PDXK (87% identical), rabbit PDXK (86% identical), mouse Pdxk (85% identical), pig PDXK (81% identical), rat Pdxk (79% identical), rat Pdxkl1 (76% identical), tropical clawed frog pdxk (70% identical), zebrafish pdxka (69% identical), zebrafish pdxkb (68% identical), and 2 more.
Diseases named in the same sentence as PDXK in open-access papers:
PDXK is named in the same sentence as 42 diseases in open-access papers, as found by Europe PMC text mining. Sharing a sentence is not in itself a finding about the gene and the disease. The quoted sentences say what the papers report.
non-small cell lung carcinoma (7 papers, 2014 to 2025). A group of at least three distinct histological types of lung cancer, including non-small cell squamous cell carcinoma, adenocarcinoma, and large cell carcinoma. "Consistently, high expression levels of PDXK have been positively correlated to survival of non-small cell lung cancer (NSCLC) patients." (PMID 38830901, 2024). "In patients with non-small cell lung carcinoma, elevated levels of PDXK was identified as a good prognostic marker." (PMID 33158037, 2020). "Inadequate intake of vitamin B6 has been associated with cancer risk and recent studies have shown that a high expression level of PDXK has a positive impact on survival of non-small cell lung cancer (NSCLC) patients." (PMID 24651653, 2014). "PDXK was demonstrated to be upregulated in non-small-cell lung cancer (NSCLC)." (PMID 32208818, 2020). "Moreover, upregulating the expression of PDXK had an apparently positive impact on the overall survival of non-small cell lung cancer patients." (PMID 32793586, 2020). "Meanwhile, an elevated level of the enzyme, pyridoxal kinase (PDXK), which facilitates the conversion of PN into PLP, was reported as a good prognostic marker in patients with non-small cell lung carcinoma." (PMID 35330159, 2022).
acute myeloid leukemia (5 papers, 2022 to 2025). Acute myeloid leukemia (AML) is a group of neoplasms arising from precursor cells committed to the myeloid cell-line differentiation. "In cancers such as acute myeloid leukemia, cells exhibit a critical addiction to the vitamin B6 metabolic pathway, selectively upregulating Pyridoxal Kinase (PDXK) to produce high levels of PLP." (PMID 41516200, 2025). "Conversely, PDXK contributes to the progression of acute myeloid leukemia and clear cell renal carcinoma (ccRCC)." (PMID 37682999, 2023). "It was reported that acute myeloid leukemia (AML) relies on PDXK kinase activity and PDXK inhibition suppresses the proliferation of AML cells." (PMID 36750831, 2023). "Indeed, this notion is supported by studies that show acute myeloid leukaemia (AML) is addicted to the vitamin B6 pathway, and genetic ablation of pyridoxal kinase (PDXK) results in the reduction of nucleic acids, polyamines and the activity of multiple PLP regulated enzymes, leading to cell death." (PMID 39408757, 2024). "A CRISPR/Cas9 functional genomic screen targeting metabolic enzymes found that pyridoxal kinase (PDXK, an enzyme that produces pyridoxal phosphate (PLP) from vitamin B6) acts an acute myeloid leukemia (AML)-selective dependency." (PMID 35178349, 2022).
diabetes (4 papers, 2019 to 2021). "Here we expressed, in dPdxk1 mutant flies, four PDXK human variants: three (D87H, V128I and H246Q) listed in databases, and one (A243G) found in a genetic screening in patients with diabetes." (PMID 31578392, 2019). "The impaired rescue of hyperglycemia displayed by the A243G variant is particularly interesting because it could be considered as a preliminary indication of the association of PDXK gene with diabetes that will be investigated in future studies." (PMID 31578392, 2019). "Studies aimed at correlating the expression of PDXK or PNPO human genes with diabetes are still scarce, but encouraging." (PMID 32456137, 2020). "This suggests that the PDXK gene could be putatively implied in human diabetes and that PLP-depleted diabetic individuals may be useful for studies aimed at dissecting the molecular mechanisms through which vitamin B6 exerts a protective role against diabetes." (PMID 34681954, 2021). "Moreover, our group also found a link between human PDXK gene and diabetes." (PMID 32456137, 2020). "Analogously PDXK variants in heterozygous condition could also impact on genome integrity in either patients treated with drugs that reduce PLP levels or also in patients affected by pathologies such as celiac disease and diabetes which per se decrease PLP levels." (PMID 31578392, 2019).
leukemia (4 papers, 2020 to 2023). A malignant (clonal) hematologic disorder, involving hematopoietic stem cells and characterized by the presence of primitive or atypical myeloid or lymphoid cells in the bone marrow and the blood. "Further preclinical and clinical studies are warranted to validate the safety and efficacy of PDXK inhibitors and other targeted therapies in the treatment of leukemia and other cancers." (PMID 38046746, 2023). "In summary, these findings strongly indicate that compound C03 holds promise as a novel inhibitor of PDXK, offering the potential for the development of effective treatments for leukemia." (PMID 38046746, 2023). "Through inhibiting PDXK, the vitamin B6 pathway can be attenuated, thereby hindering the reproduction of leukemia cells." (PMID 37234150, 2023). "The study's implications are significant, suggesting that compound C03 holds promise as an inhibitor of PDXK, potentially offering a targeted therapy for leukemia." (PMID 38046746, 2023). "This research offers valuable insights into the development of targeted therapies for leukemia and underscores the significance of PDXK as a therapeutic target in the fight against cancer." (PMID 38046746, 2023). "The identification of PDXK as a potential leukemia target holds promise, as this enzyme plays a pivotal role in the progression of cancers." (PMID 38046746, 2023). "However, further preclinical and clinical studies are needed to evaluate the safety and efficacy of PDXK inhibitors and other targeted therapies for the treatment of leukemia." (PMID 38046746, 2023). "Consistently, pharmacological inhibition of PDXK using isoniazid or the more specific 4′-O-methylpyridoxine (gingkotoxin) has the same effect as genetic depletion of PDXK, suggesting that vitamin B6 in plasma supports leukaemia proliferation." (PMID 32208818, 2020). "An intriguing link has emerged between elevated expression levels of PDXK and PLP and various types of carcinomas, including leukemia." (PMID 38046746, 2023).
Hyperglycemia (3 papers, 2019 to 2020). An increased concentration of glucose in the blood. "We demonstrated that the expression, in dPdxk1 mutant flies, of 4 PDXK variants with impaired catalytic activity or affinity for substrates was unable to rescue the hyperglycemia due to dPdxk1 mutation, from the wild-type PDXK protein." (PMID 32456137, 2020). "This approach has been employed to further confirm the role of PDXK human gene in chromosome integrity maintenance and to strengthen the model in which CABs are largely produced by hyperglycaemia in low PLP conditions." (PMID 32208818, 2020).
lung cancer (3 papers, 2012 to 2025). A malignant neoplasm involving the lung. "Five prognostic genes, including HPSE, DENND1C, GRWD1, HLA‐DQA1, and PDXK, were identified to further develop a risk signature, which exhibited moderate power for forecasting the prognosis of lung cancer patients in training, testing, and validation sets." (PMID 41031217, 2025). "High expression level of Pyridoxal kinase (PDXK) has been positively correlated with survival of nonsmall cell lung cancer (NSCLC) patients." (PMID 30061626, 2018).
neuropathy (3 papers, 2019 to 2025). A disorder affecting the nervous system that manifests with pain, tingling, numbness, and/or muscle weakness. "Analogies can be drawn with both the recessive mutations in PDXK, which cause a B6‐responsive inherited motor and sensory neuropathy due to reduced enzymatic conversion of pyridoxal to PLP22, and the neuropathy caused by nutritional B6 deficiency." (PMID 39444079, 2025). "Clinically, the PDXK‐related neuropathy presented with mixed sensory and motor involvement in early childhood and was associated with optic atrophy later in adulthood." (PMID 31187503, 2019). "Compounds that inhibit PDXK decrease GABA production, which may cause neurological hyperexcitability and seizures, though the precise mechanism by which PDXK causes neuropathy is yet unclear." (PMID 40809450, 2025).
optic atrophy (3 papers, 2019 to 2023). A disorder characterized by loss of optic nerve fibers. "Hereditary polyneuropathy with optic atrophy can occur due to a PDXK variant leading to impaired vitamin B6 metabolism." (PMID 35240026, 2022). "We identified biallelic mutations in PDXK in 5 individuals from 2 unrelated families with primary axonal polyneuropathy and optic atrophy." (PMID 31187503, 2019). "Here, we show that biallelic mutations in PDXK lead to peripheral neuropathy with optic atrophy." (PMID 31187503, 2019).
breast carcinoma (2 papers, 2019 to 2024). "Higher PDXK was associated with an increased risk of breast cancer." (PMID 38684708, 2024).
colorectal cancer (2 papers, 2018 to 2023). A primary or metastatic malignant neoplasm that affects the colon or rectum. "Hyperactive lysosomes resulted in the continuous degradation of PDXK and B6 deficiency that promoted proliferation in Wnt-driven colorectal cancer (CRC) cells." (PMID 37682999, 2023). "For instance, modified APA patterns have been reported during the progression of colorectal cancer, affecting three genes: dermokine (DMKN), pyridoxal kinase (PDXK), and peptidylpropyl isomerase E (PPIE)." (PMID 29495341, 2018).
myeloid leukaemia (2 papers, 2020 to 2023). "Among the top six compounds, compound C03 with minimal IC50 of 9.97μM in K562 cells (myeloid leukemia), downregulates the expression of endogenous PDXK in a dose-dependent manner in K562 leukemic cells." (PMID 38046746, 2023). "Analogously, PDXK was recently found to be abundantly expressed in myeloid leukaemia cells, where PDXK depletion has an antiproliferative effect, which neither PN nor PM was able to rescue." (PMID 32208818, 2020).
pancreatic ductal adenocarcinoma (2 papers, 2024). An infiltrating adenocarcinoma that arises from the epithelial cells of the pancreas. "Previous studies have linked PDXK to the progression of pancreatic ductal adenocarcinoma (PDAC)." (PMID 38833016, 2024). "CircFOXK2 promoted pancreatic ductal adenocarcinoma (PDAC) progression by interacting with YBX1 and hnRNPK proteins to upregulate the expression of NUF2 and PDXK oncogenes." (PMID 38890620, 2024).
axonal sensory neuropathy (1 paper, 2025). "Genetic PDXK deficiency can lead to axonal sensory neuropathy, and high doses of PN, which inhibit PDXK function, may create comparable symptoms." (PMID 40809450, 2025).
Charcot-Marie-Tooth (CMT) disease (1 paper, 2023). "This review considers the enzymes encoded by the DHTKD1, PDK3 and PDXK genes, whose mutations are observed in patients with Charcot-Marie-Tooth (CMT) disease." (PMID 37508330, 2023).
epilepsy (1 paper, 2020). A brain disorder characterized by episodes of abnormally increased neuronal discharge resulting in transient episodes of sensory or motor neurological dysfunction, or psychic dysfunction. "It has been reported that the function of PDXK is prominently enhanced in the whole brain tissue of humans, embryos, and fetuses, as well as in the whole brain of in epilepsy-prone and epilepsy-resistant rats." (PMID 32793586, 2020).
esophageal carcinomas (1 paper, 2022). A primary or metastatic malignant neoplasm involving the esophagus. "PDxK and GSTP1 expressions have been previously correlated to resistance to platinum-based chemotherapy in ovarian and esophageal carcinomas." (PMID 35565353, 2022).
Hypertension (1 paper, 2024). The presence of chronic increased pressure in the systemic arterial system. "However, lowering PDXK was also associated with higher systolic [Beta: 0.72, 95% CI: 0.49 to 0.95; PP4: 0.92] and diastolic blood pressure (mmHg) [Beta: 0.51, 95% CI: 0.38 to 0.64; PP4: 0.96], a higher risk of having hypertension [OR: 1.12, 95% CI: 1.07 to 1.15; PP4: 0.90]." (PMID 38684708, 2024).
metastatic disease (1 paper, 2022).
ovarian carcinoma (1 paper, 2023). A malignant neoplasm originating from the surface ovarian epithelium. "PDXK was highly expressed in ovarian cancer tissues and cells, and high PDXK expression was positively correlated with poor differentiation, advanced FIGO stage, and worse prognosis." (PMID 36750831, 2023).
polyneuropathy (1 paper, 2019). A disease or disorder affecting more than one nerve. "Therefore, we recommend that PDXK mutations should be screened for in patients with autosomal recessive early onset polyneuropathy, and supplementation with PLP should be started promptly with long‐term monitoring of clinical outcomes." (PMID 31187503, 2019).
cancer (14 papers, 2014 to 2025). A tumor composed of atypical neoplastic, often pleomorphic cells that invade other tissues. "The low levels of B6 in cancer hint at a role for PDXK; however, the presence of PDXK mutations in cancer is less defined." (PMID 37682999, 2023). "Several phosphorylations decorate PDXK (multiple of which are mutated in cancer patients), although the effects of these post-translational modifications (PTMs) have yet to be defined." (PMID 36295863, 2022). "In this work, we investigated whether human PDXK variants present in the population can impact on DNA integrity and be considered predictive of an increased cancer risk." (PMID 31578392, 2019). "Although these variants are rare in population and carried in heterozygous condition, our findings suggest that in certain metabolic contexts and diseases in which PLP levels are reduced, the presence of these PDXK variants could threaten genome integrity and increase cancer risk." (PMID 31578392, 2019). "PDXK is involved in carcinogenesis, progression, and responses to therapy in cancers due to its role in vitamin B6 metabolism." (PMID 41031217, 2025). "Our study provides new insight into the development of novel and potent anti-cancer drugs targeting the PDXK-PLP complex with minimal side effects using in-silico molecular docking and in-vitro cell-based studies." (PMID 38046746, 2023). "In a preceding study, we have made a substantial impact on the realm of cancer research by designing inhibitors targeted at the specific site of PDXK." (PMID 38046746, 2023). "Results suggested that the expression of PDXK was upregulated in the HCC cancer samples compared with para-tumor normal samples." (PMID 36750831, 2023). "Altogether, our findings provide compelling evidence for the utility of compound C03 as an effective inhibitor of PDXK and highlight its potential for advancing the development of targeted therapies against cancer." (PMID 38046746, 2023). "In our research, we found that the metastasis and proliferation of HCC cancer cells were compromised by the knockdown of PDXK." (PMID 36750831, 2023). "Leukemic cells have an increased need for vitamin B6 to sustain their survival and rapid growth, highlighting the potential of targeting PDXK-PLP as a promising therapeutic target in cancer treatment." (PMID 38046746, 2023). "The expression of PDXK was detected in multiple LICH cancer cell lines, including CCC-HEL-1, Hep-3B, MHCC-LM3, Huh-7, MHCC-97H, SK-Hep-1, Hep-G2, SMMC-7721, and BEL-7402." (PMID 36750831, 2023). "It highlights the importance of PDXK as a therapeutic target in cancer treatment and provides insights into the compound's mechanism of action." (PMID 38046746, 2023). "In AML cancerous states, PDXK constitutively phosphorylates PL and PN into PLP, thereby promoting cancer cell proliferation, while a dominant negative PDXK mutant was unable to restore PLP levels or the proliferative effects of AML cells." (PMID 36295863, 2022). "According to several studies, PDXK may suppress tumors in a variety of cancers and downregulation of PDXK expression may contribute to tumor growth and progression." (PMID 38046746, 2023). "Given this, genetic and metabolic dissection of these cancers relative to those where B6 is protective could help to elucidate the specific mechanisms through which PDXK tunes tumorigenic processes." (PMID 37682999, 2023). "Therefore, targeting PDXK with small molecule inhibitors or other therapeutic approaches may represent a promising strategy for cancer treatment." (PMID 38046746, 2023). "Further studies are necessary to finalize the effect of the THI in cancer progression because THI is also suggested to be a direct inhibitor of pyridoxal kinase and might inhibit SPL directly or inhibit the cofactors required to catalyse S1P irreversibly through pyridoxal kinase inhibition." (PMID 36125914, 2022).